TTR (transthyretin)
Diseases named in the same sentence as TTR in open-access papers (continued):
Sharing a sentence is not in itself a finding about the gene and the disease.
hippocampal atrophy (2 papers, 2011 to 2016). "A recent analysis of TTR single nucleotide polymorphisms (SNPs) in the MIRAGE study of AD families has associated 5 TTR SNPs with hippocampal atrophy." (PMID 22112803, 2011). "Moreover, TTR is a well established biomarker for AD: 1) a decrese in the CSF and serum TTR levels has been associated to an increased AD severity and faster rate of disease progression and 2) 5 SNPs and different TTR haplotypes have been related to hippocampal atrophy." (PMID 27249223, 2016).
hyperthyroidism (2 papers, 2015 to 2023). Overactivity of the thyroid gland resulting in overproduction of thyroid hormone and increased metabolic rate. "In case of hyperthyroidism, only minor differences in PTM pattern of TTR were detectable in comparison to euthyroid patients." (PMID 25311081, 2015).
hypogonadism (2 papers, 2020 to 2025). A disorder characterized by decreased function of the gonads. "In a smaller exploratory study of 19 otherwise healthy men presenting for evaluation of possible hypogonadism, pre-albumin (a.k.a.transthyretin, a marker of anabolism) and testosterone were measured." (PMID 30670838, 2020).
leukemia (2 papers, 2023 to 2025). A malignant (clonal) hematologic disorder, involving hematopoietic stem cells and characterized by the presence of primitive or atypical myeloid or lymphoid cells in the bone marrow and the blood. "The relationship between serum transthyretin levels and overall survival (OS) and leukemia-free survival (LFS) were analyzed by Kaplan–Meier analysis and Cox Regression Model." (PMID 36960201, 2023). "Notably, lower transthyretin could predict an increased risk of death independently of both IPSS-R and IPSS-M, and a high risk of progression to leukemia independently of IPSS-M, which has not been reported in previous literature, as far as we know." (PMID 36960201, 2023).
lymph node metastases (2 papers, 2009 to 2017). "Patients with lymph node metastasis showed increased serum concentrations of sVCAM-1 and transthyretin." (PMID 19400944, 2009).
mental disorder (2 papers, 2015 to 2018). A disease that has its basis in the disruption of mental process. "All these studies highlight the importance of neurosecretory protein VGF and TTR in neurological/psychiatric disorders." (PMID 25256248, 2015). "APP is another protein that binds to TTR and its role in mental disorders is reported." (PMID 30034649, 2018).
migraine (2 papers, 2021 to 2024). "Finally, two proteins were down-regulated in both groups of patients with migraine vs CTRL, including apolipoprotein A-I (APOA1) and alpha-1-antitrypsin (A1AT), while two protein spots, identified as transthyretin (TTHY) and pepsin A-3 (PEPA3), were up-regulated in the same comparison." (PMID 33923220, 2021).
muscular dystrophies (2 papers, 2017 to 2021). "Based on these functions, TTR has great potential for use in the strategic development of novel therapeutics to combat muscular dystrophies." (PMID 28075349, 2017).
myocardial disease (2 papers, 2018 to 2024). "99mTechnetium-HDP (HDP) bone scans differentiate transthyretin (ATTR) cardiac amyloid from other infiltrative myocardial diseases." (PMID 30175320, 2018).
pneumonia (2 papers, 2021 to 2025). An acute, acute and chronic, or chronic inflammation focally or diffusely affecting the lung parenchyma, caused by an infection in one or both of the lungs (by bacteria, viruses, fungi, or mycoplasma.). "For these reasons, nutritional assessments using only albumin, prealbumin, or transthyretin are not appropriate for dysphagia patients who are prone to acute inflammation such as pneumonia." (PMID 33673581, 2021).
polycystic kidney disease (2 papers, 2025). A usually autosomal dominant and less frequently autosomal recessive genetic disorder characterized by the presence of numerous cysts in the kidneys leading to end-stage renal failure. "The other 7 positive tests included amyloidosis (TTR, N = 3), Alport syndrome (COL4A3, N = 2), polycystic kidney disease (PKD1, N = 1), and susceptibility to ESRD (APOL1, N = 1)." (PMID 40126616, 2025).
protein deficiency (2 papers, 2018 to 2022). "TTR is a plasma protein endowed with a number of functional properties and is now widely used both in developing areas for the nutritional assessment and follow-up of underprivileged populations and in developed countries to identify those hospitalized patients at risk of protein-deficiency." (PMID 30233492, 2018).
protein-energy malnutrition (2 papers, 2013 to 2018). A nutritional deficit that is caused by inadequate protein or calorie intake. "Protein-energy malnutrition has been associated with reduced hepatic synthesis of retinol binding protein (RBP) and transthyretin used to transport VA in the body." (PMID 24028603, 2013).
pulmonary TB (2 papers, 2019 to 2022). "However, the performance of this modified signature was reduced, compared to what was reported in adults with pulmonary TB, albeit, with transthyretin in place of NCAM1 in the adult study." (PMID 31612118, 2019).
renal cell carcinoma (2 papers, 2022 to 2025). "In contrast, thyroid transcription factor 1 (TTF-1), anti-renal cell carcinoma (RCC), CD10, CK20, as well as synaptophysin, chromogranin A, thyroglobulin and transthyretin are negative." (PMID 35546652, 2022).
retinal degeneration (2 papers, 2010 to 2012). Degeneration of the retina. "Analysis of RBP4, TTR and levels of retinol in serum further established the effect of c.111+1G>A mutation and its association with the retinal degeneration phenotype observed in this pedigree." (PMID 23189188, 2012). "At 14 days of age, instead, all TTR flies showed signs of retinal degeneration, varying from a mild phenotype in TTRwt flies to strong degeneration in TTR-A flies, especially in those carrying two TTR-A copies." (PMID 21179560, 2010). "Since the retina is the principal source of TTR in our model, retinal degeneration might be relevant for the explanation of the temporal development of the phenotype." (PMID 21179560, 2010).
squamous carcinoma (2 papers, 2015 to 2021). "According to research, overexpression of TTR is discovered in the blood of human patients with adenocarcinoma, squamous carcinoma, and small cell lung cancer." (PMID 34066808, 2021).
venous thromboembolism (2 papers, 2021 to 2025). Occlusion of the lumen of a vein by a thrombus that has migrated from a distal site via the blood stream. "The involvement of TTR in fibrinolysis–coagulation balance confirms the connection of TTR level with venous thromboembolism." (PMID 34359938, 2021). "TTR was shown to be the strongest plasma biomarker candidate for future venous thromboembolism." (PMID 34359938, 2021).
visceral leishmaniasis (2 papers, 2011 to 2023). A severe form of leishmaniasis characterized by irregular bouts of fever, substantial weight loss, swelling of the spleen and liver, and anemia (which may be serious). "These derivatives possessed different inhibitory activities against cancer cells, Trypan osoma brucei and Visceral Leishmaniasis, and selectively targeted tyrosine kinase, proteasome, and transthyretin amyloidogenesis." (PMID 37049976, 2023). "The up-regulation of C1 inhibitor and the down-regulation of transthyretin and apolipoprotein A-I in visceral leishmaniasis were thus confirmed in these samples." (PMID 21906353, 2011). "Decreased transthyretin level is described in visceral leishmaniasis in a study with a small sample size previously." (PMID 21906353, 2011). "We identified alpha-1-acidglycoprotein and C1 inhibitor as up regulated and transthyretin, retinol binding protein and apolipoprotein A-I as down regulated proteins in visceral leishmaniasis sera in comparison with healthy controls." (PMID 21906353, 2011). "Relative abundance of C1 inhibitor in control was 33920.4 ± 8991.7 and in visceral leishmaniasis was 54101.0 ± 27858.3 (p < 0.01) Relative abundance of transthyretin in control was 22236.7 ± 2794.3 and in visceral leishmaniasis was 12804.3 ± 6128.6 (p < 0.0001)." (PMID 21906353, 2011).
vitreous hemorrhage (2 papers, 2014 to 2022). Blood extravasation in the vitreous humor. "We identified that the p.G103R mutation of the TTR gene in a Han Chinese family was associated with vitreous hemorrhage." (PMID 36186469, 2022).
acromegaly (1 paper, 2017). Acromegaly is an acquired disorder related to excessive production of growth hormone (GH) and characterized by progressive somatic disfigurement (mainly involving the face and extremities) and systemic manifestations. "However, TTR was decreased in bGH plasma and the serum of patients with acromegaly." (PMID 28670222, 2017).
acute leukemia (1 paper, 2023). A clonal (malignant) hematopoietic disorder with an acute onset, affecting the bone marrow and the peripheral blood. "Among the 280 newly diagnosed patients with MDS, 17 patients in the low transthyretin group progressed to acute leukemia, and 83 patients died." (PMID 36960201, 2023). "In the normal transthyretin group, 17 patients progressed to acute leukemia, and 53 patients died." (PMID 36960201, 2023).
advanced heart failure (1 paper, 2023). Patients with advanced heart failure have severe limitations, experiences symptoms even while at rest and are mostly bedbound patients. "Persistent mild increase in troponin levels on repeated tests.Increased NT-proBNP values (> 5000 pg/mL) in non-advanced heart failure Low serum transthyretin values." (PMID 35929637, 2023).
alcoholic hepatitis (1 paper, 2023). Acute hepatitis resulting from ingestion of alcohol. "The promoter regions of TTR and other negative APP contain HNF-4α binding sites, and this correlation has been observed in patients with alcoholic hepatitis." (PMID 36652164, 2023).
allergic rhinitis (1 paper, 2005). Inflammation of the nasal mucous membranes caused by an IgE-mediated response to external allergens. "The small up-regulation of transthyretin detected in allergic individuals (1.6-fold) is probably due to the increased plasma exudation seen in allergic rhinitis." (PMID 16236163, 2005).
amyloidoma (1 paper, 2022). Nodular localized form of amyloidosis with predominantly thoracic localization (pulmonary amyloidosis), considered as secondary protein structure disease in which insoluble protein fibrils accumulate extracellularly. "Amyloid light chain and beta-2-microglobulin are the most common types, with only three previous reports of transthyretin (ATTR) Amyloidoma." (PMID 36109706, 2022). "We present a case of a 71-year-old patient with transthyretin (ATTR) type cervical amyloidoma and provide a review of literature on amyloidoma involving the cervical spine." (PMID 36109706, 2022).
anhaptoglobinemia (1 paper, 2014). "By use of this strategy, we were able to show, for the first time, that T4 and its carrier protein, TTR, were elevated in the serum of heroin addicts, and that the occurrence of Hp phenotype Hp0 (anhaptoglobinemia) is associated with heroin addiction." (PMID 24743330, 2014).
ascending aortic aneurysm (1 paper, 2024). "We report a patient with ascending aortic aneurysm and chronic abdominal aortic dissection who had significant wild-type transthyretin amyloid deposition on surgical pathology." (PMID 38576771, 2024).
autoimmune liver disease (1 paper, 2012). "In the TTR-NP model of AIH, previous liver inflammation is not necessary, but the autoimmune liver disease is observed several months after DNA vaccination." (PMID 23110209, 2012).
breast tumor (1 paper, 2022). "It is known that rarely (only in 7% of cases) aggregated amyloid, predominantly light‐chain amyloidosis (AL) or sometimes misfolded transthyretin (TTR)‐type amyloid, are detected in human breast tumor samples." (PMID 34592066, 2022).
cerebral infarction (1 paper, 2026). An ischemic condition of the brain, producing a persistent focal neurological deficit in the area of distribution of the cerebral arteries. "This suggests that TTR may be an independent predictor of positive clinical outcome, estimating that high serum concentration of TTR may be a prognostic indicator for the outcome of cerebral infarction." (PMID 41595476, 2026).
cholangiocarcinoma (1 paper, 2015). A carcinoma that arises from the intrahepatic biliary tree (intrahepatic cholangiocarcinoma) or from the junction, or adjacent to the junction, of the right and left hepatic ducts (hilar cholangiocarcinoma). "Other tumor markers that have been studied for diagnosis of cholangiocarcinoma include transthyretin (TTR), interleukin-6 (IL-6), mucin-5AC (MUC5AC) and matrix metalloproteinase-7 (MMP-7)." (PMID 25355800, 2015).
choroid plexus neoplasm (1 paper, 2013). An intraventricular papillary neoplasm that originates from the choroid plexus epithelium. "Transthyretin and cytokeratin are reliable markers of choroid plexus neoplasms." (PMID 22752623, 2013).
chronic polyneuropathy (1 paper, 2023). Polyneuropathy that is persistent or long-standing in nature. "Within the study period, 338 patients with chronic polyneuropathy underwent TTR gene sequencing, of which 92 patients were ultimately diagnosed with CIAP." (PMID 37266816, 2023). "In this study, the yield of TTR gene sequencing in a population of patients with chronic polyneuropathy was 3% (10/338), but none of the identified patients with ATTRv-PN had a clinical presentation typical of CIAP." (PMID 37266816, 2023).
co-infection (1 paper, 2009). "In patients with HEV infection, whether with or without HBV co-infection, the plasma transthyretin levels were significantly lower than those in healthy controls." (PMID 19860894, 2009).
congenital heart malformation (1 paper, 2025). A disease that has its basis in the disruption of heart development. "The TTR variant observed in the current study has been classified in ClinVar as pathogenic and is associated with congenital heart malformations." (PMID 41296379, 2025).
cortical atrophy (1 paper, 2014). "In this study we identified RANTES, NSE, and transthyretin, in addition to Clusterin, to be associated with cortical atrophy in the MCI group, with Clusterin showing the strongest correlation with all brain regions assessed." (PMID 25012867, 2014).
cyst (1 paper, 2012). A sac-like closed membranous structure that may be empty or contain fluid or amorphous material. "The peaks with highest ROC AUC for each protein in cyst fluid (PCI, ApoC-III, ApoC-I, SAA4 and TTR) were selected for further statistical analysis together with corresponding serum CA125." (PMID 23268721, 2012).
Dent disease (1 paper, 2004). Dent disease is a rare genetic renal tubular disease characterized by manifestations of proximal tubule dysfunction. "The involvement of the megalin receptor in the tubular reabsorption of filtered TTR has been shown in patients with Dent's disease." (PMID 15341658, 2004).
Down syndrome (1 paper, 2022). "Several cytoskeleton proteins have been linked to CHD or related malformations, such as the association of decreased maternal plasma transthyretin with fetal Down syndrome accompanied by CHDs, and four cytoskeleton proteins in maternal plasma as potential biomarkers for detecting CHDs in offspring." (PMID 35590261, 2022).
endometrioid adenocarcinoma (1 paper, 2007). An adenocarcinoma characterized by the presence of malignant glandular epithelial cells resembling endometrial cells. "Multiple logistic regression models (MLRM) were constructed utilizing all biomarker values (CA125, TTR, TF and apoA-I) from all histological subtypes (serous, mucinous, and endometrioid adenocarcinoma)." (PMID 19662218, 2007).
eosinophilia (1 paper, 2022). "In particular, we detected upregulation of certain protein species of APOA1, APOC-II, and APOC-III, which resulted as negatively correlated with peripheral eosinophilia (cell/mm3%) and upregulation of certain protein species of the antioxidants ceruloplasmin and transthyretin." (PMID 35453511, 2022).
familial Alzheimer disease (1 paper, 2018). A degenerative disease of the brain that causes gradual loss of memory, judgment, and the ability to function socially. "TTR is expressed in neurons during heat shock and during the progression of mouse models of familial Alzheimer’s disease." (PMID 30111340, 2018).
Fanconi syndrome (1 paper, 2019). "In Fanconi syndrome, the megalin-receptor-mediated endocytosis of LMWPs is disturbed, resulting in the increased excretion of albumin, prealbumin (transthyretin, 55 kDa), α1-acid glycoprotein (40 kDa), and other LMWPs." (PMID 31781392, 2019).
hemangiosarcoma (1 paper, 2022). "Of note, one mouse from the TTR-PolyA group presented with a hemangiosarcoma in his spleen and granulomas in his liver." (PMID 36507314, 2022).
hepatobiliary tumor (1 paper, 2023). "We found that TTR had a promotive effect on the invasive ability of hepatobiliary tumor cells under co‐culture conditions with TAMs." (PMID 37688511, 2023).
heroin dependence (1 paper, 2014). Physical and psychological dependence on the drug heroin. "The 6 protein spots with an increase upon heroin dependence were identified as immunoglobulin J chain (spots 1 and 2), transthyretin (spot 3 and 7), haptoglobin (spot 4), and vitronectin (spot 6)." (PMID 24743330, 2014).
hyperhomocysteinemia (1 paper, 2004). A serious metabolic condition caused by mutations in the MTHFR gene, medications, or nutritional deficiency. "Additionally, the S-homocysteinylation of TTR has been described in plasma of humans with hyperhomocysteinemia." (PMID 15341658, 2004).
hypertriglyceridemia (1 paper, 2018). A laboratory test result indicating elevated triglyceride concentration in the blood. "In particular, our results indicate that TTR may play a role in the pathophysiology of diabetic hypertriglyceridemia." (PMID 29747616, 2018). "Similarly, subjects in the highest TTR and HOMA-IR tertiles had 3.5 times (OR = 3.46, 95% CI = 1.30–9.20) and 3.6 times (OR = 3.58, 95% CI = 1.33–9.58) higher risk of developing hypertriglyceridemia, respectively, than those in the lowest tertiles." (PMID 29747616, 2018). "In addition, the risk of hypertriglyceridemia was approximately 4-fold greater in subjects with high serum RBP4 and TTR levels and HOMA-IR values." (PMID 29747616, 2018).
hypopituitarism (1 paper, 2025). A condition of diminution or cessation of secretion of one or more hormones from the anterior pituitary gland. "For example, of patients who develop TTR-HO, about 80% consult for AVP-D and about 84% consult for hypopituitarism during the study period." (PMID 39814823, 2025). "Of the primary diagnoses related to TTR-HO, tumor-related follow-up visits were most frequent (88%), followed by AVP-D (9%), and hypopituitarism (3%)." (PMID 39814823, 2025).
lymphangiectasia (1 paper, 2021). "After the mass spectrometry analysis, we identified 15 main spots, three of which (M, N, and S), corresponding to the Fc fragment of IgG binding protein (Fcgbp), transthyretin (TTR), and proproteinase E, respectively, were present in the feces of dogs with lymphangiectasia but not in healthy dogs." (PMID 34679072, 2021).
mastitis (1 paper, 2022). Inflammation of breast tissue during lactation or postpartum due to an obstructed duct or infection. "Proteins that stand out as logical candidates for further analyses include various APPs and vascular-derived proteins such as C3, C4, TF, ALB, TTR, FGA, and ITIH4 in mastitis whey of E. coli infected cows by 2-DE and label-free methods, respectively." (PMID 36335251, 2022).
memory (1 paper, 2015). The activities involved in the mental information processing system that receives (registers), modifies, stores, and retrieves informational stimuli. "We observed subependymal TTR amyloid and myelin loss in hippocampal efferent tracts including the alveus, fimbria and fornix that may underlie our patient’s memory deficit." (PMID 26156087, 2015).